ITIH4 (inter-alpha-trypsin inhibitor heavy chain 4)
Description:
Type II acute-phase protein (APP) involved in inflammatory responses to trauma. May also play a role in liver development or regeneration.
Synonyms: ITI-HC4; IHRP; Gp120; PK-120; ITIHL1; PK120; H4P
Tractability: Antibody: its Gene Ontology location is reachable by antibodies, with high confidence; UniProt places it where antibodies can reach, with medium confidence; UniProt predicts a signal peptide or a membrane-spanning region. PROTAC: its protein half-life has been measured.
Gene: Protein-coding gene on chromosome 3 (52,812,918 to 52,831,069, reverse strand). Ensembl gene ENSG00000055955.
Subcellular location: Secreted
Subcellular location (Human Protein Atlas): Vesicles; Predicted to be secreted
Pathways (Reactome):
Hemostasis: Platelet degranulation
Gene Ontology:
Molecular function: protein binding; endopeptidase inhibitor activity; serine-type endopeptidase inhibitor activity
Biological process: acute-phase response; response to cytokine; hyaluronan metabolic process
Cellular component: blood microparticle; extracellular exosome; extracellular matrix; extracellular region; platelet dense granule lumen
Genetic constraint (gnomAD): Loss-of-function variants: 80 observed, 115.58 expected, observed/expected ratio (o/e) 0.69, 90% interval 0.58 to 0.83. The upper end of that interval is the gene's LOEUF score, 0.83, which puts it in group 3 of 6, group 1 being the genes least tolerant of losing a copy. Missense variants: 1,055 observed, 1,234.1 expected, observed/expected ratio (o/e) 0.85, 90% interval 0.81 to 0.9. Synonymous variants: 469 observed, 486.98 expected, observed/expected ratio (o/e) 0.96, 90% interval 0.89 to 1.04.
Homologues: Orthologues: chimpanzee ITIH4 (99% identical), macaque ITIH4 (90% identical), pig ITIH4 (71% identical), dog ITIH4 (71% identical), guinea pig ITIH4 (69% identical), mouse Itih4 (66% identical), rat Itih4 (65% identical), rabbit ITIH4 (61% identical). Paralogues in human: ITIH3 (40% identical), ITIH1 (34% identical), ITIH2 (33% identical), ITIH6 (30% identical), ITIH5 (29% identical), PARP4 (18% identical), VWA3B (16% identical), VWA5B1 (15% identical), VWA3A (14% identical), VWA5A (14% identical), VWA5B2 (13% identical).
Diseases named in the same sentence as ITIH4 in open-access papers:
ITIH4 is named in the same sentence as 193 diseases in open-access papers, as found by Europe PMC text mining. Sharing a sentence is not in itself a finding about the gene and the disease. The quoted sentences say what the papers report.
viral infection (73 papers, 2006 to 2025). "Increased levels of the ITIH4 (inter-alpha-trypsin inhibitor heavy chain 4) protein are associated with such disorders as human immunodeficiency and virus infection." (PMID 39062058, 2024). "Altered expression of ITIH4 at protein level in sera was found in a number of cancers as well as obstructive pulmonary disease or bacterial and viral infections." (PMID 31238892, 2019).
Cognitive impairment (18 papers, 2014 to 2026). Abnormal cognition is characterized by deficits in thinking, reasoning, or remembering. "We identified liver‐derived blood proteins C3, HP, ITIH4, and SAA1 as the candidate molecules associated with cognitive impairment based on the proteomics of mouse liver and blood, as well as the transcriptomic and proteomic profiles of human organs." (PMID 41221556, 2026).
schizophrenia (17 papers, 2013 to 2025). A major psychotic disorder characterized by abnormalities in the perception or expression of reality. "Schizophrenia-associated variants in ITIH4 have been shown to regulate expression of ITIH4 in the prefrontal cortex, and variants in ITIH4 is a biomarker for COPD." (PMID 38830989, 2024). "For example, ITIH4 is associated with schizophrenia and CHD7 is implicated in autism." (PMID 31784694, 2019). "This region harbours genes including ITIH4, NEK4, GNL3 and PBRM1 that have previously been linked mechanistically to schizophrenia and related brain changes at cellular and whole brain scales." (PMID 38016951, 2023). "The genomic region of chromosome 3p21.1 contained several genes pleiotropically associated with both SA and schizophrenia, including PBRM1, NEK4, GNL3, ITIH4 and NISCH." (PMID 38016951, 2023). "One example is the inter-alpha-trypsin inhibitor heavy chain gene family (ITIH1, ITIH3, ITIH4), which has been associated with major psychiatric disorders including MDD, bipolar disorder and schizophrenia." (PMID 30626913, 2020). "It has been shown that, in the blood plasma of patients with MDD in comparison with healthy controls, the ITIH4 protein concentration is significantly higher but not in patients with schizophrenia or bipolar disorder." (PMID 39062058, 2024). "Many of these genes have been previously linked to brain-related disorders, including Alzheimer’s disease (WDR12, AGFG2, and CDK5RAP3), schizophrenia (SRA1, WDR55, CORO7, DDAH2, PCDHA8), autism spectrum disorder (MAPK3, PCDHA13), and major depressive disorder (ZMAT2 and ITIH4)." (PMID 39269986, 2024). "Notably, ITIH3, ITIH4, and NT5C2 were selected for depression, while PSMA4 and ITSN1 were identified for schizophrenia." (PMID 38637810, 2024).
endothelial dysfunction (13 papers, 2009 to 2024). In vascular diseases, endothelial dysfunction is a systemic pathological state of the endothelium (the inner lining of blood vessels) and can be broadly defined as an imbalance between vasodilating and vasoconstricting substances produced by (or acting on) the endothelium. "From the 14 upregulated exosomal proteins, FBG, FGG, ITIH4, and SERPINA3 coding gene for alpha-1-antichymotrypsin were associated to endothelial dysfunction and coagulation cascade activation and platelet degranulation." (PMID 33535467, 2021).
depression (12 papers, 2015 to 2024). "Multivariate logistic regression analysis revealed that serum levels of TUBB, ITIH4, C3, and C4A were significant independent risk factors for the development of depression." (PMID 38895030, 2024). "Comparing the shared genes in TWAS of whole blood with the shared proteins in PWAS, we found that the protein-coding gene ITIH4 reached significant levels of mRNA and protein in three pairs of traits of depression, BD and SCZ." (PMID 39588545, 2024). "Our study on plasma proteomics for depression demonstrated that TUBB, ITIH4, C3, and C4A differentiate between depression patients and healthy controls." (PMID 38895030, 2024). "The results of the control group ELISA showed that serum levels of TUBB, ITIH4, C3 and C4A were significantly higher in patients with depression than in healthy controls." (PMID 38895030, 2024). "STRING software showed that ITIH4, C3, C4A and TUBB were involved in the pathogenesis of depression through an unknown pathway." (PMID 38895030, 2024). "For example, proteomic research suggests that the serum levels of c-reaction protein (CRP), inter-alpha-trypsin inhibitor heavy chain H4 (ITIH4), serum amyloid A1 (SAA1), and angiopoietin-like 3 (ANGPTL3) are significantly higher in patients with depression than in healthy controls." (PMID 31719821, 2019).
hepatocellular carcinoma (11 papers, 2014 to 2024). A malignant tumor that arises from hepatocytes. "Itih4 has been confirmed to be an important marker associated with liver cancer, early gastric cancer, and hepatocellular carcinoma diagnosis." (PMID 35578660, 2022). "ITIH4, inter-alpha-trypsin inhibitor heavy chain 4, is an acute response protein that is secreted primarily by the liver and associated with hepatocellular carcinoma." (PMID 33718182, 2021). "In addition, ITIH4 is known to be associated with other cancers like hepatocellular carcinoma and gastric cancer." (PMID 38350915, 2024). "As such, circulating ITIH3/4 levels are associated with carcinogenesis in colorectal cancer, and high ITIH4 levels correlate with a better prognosis in hepatocellular carcinoma." (PMID 38888758, 2024). "Many studies have found that ITIH4 is involved in chronic liver diseases, including chronic viral hepatitis, autoimmune liver disease, and hepatocellular carcinoma." (PMID 37280603, 2023). "ITIH4 is a liver-specific protein involved in the inflammatory reaction to a trauma and reported in a hepatocellular carcinoma study." (PMID 35216175, 2022). "Another member, ITIH4, has been demonstrated as a potential diagnostic marker in hepatocellular carcinoma (HCC) that was even superior to AFP; it exhibited a strikingly lower concentration in HCC than normal controls and its expression level was declining during the progression of HCC." (PMID 33744857, 2021). "In two proteomic studies, ITIH3/ITIH4, as one of the serum differential proteins, was detected from the patients of hepatocellular cancer or gastric cancer, indicating a potential relation of ITIH3/ITIH4 to digestive system cancers." (PMID 31481982, 2019).
COVID-19 (10 papers, 2021 to 2024). A disease caused by infection with severe acute respiratory syndrome coronavirus 2. "We quantified plasma concentrations of C1-INH, AT, α2M and ITIH4, and identified multiple associations between protease inhibitor levels and COVID-19 severity." (PMID 34458849, 2021). "Mass spectrometry-based proteomic studies have identified associations between COVID-19 and protease inhibitors, including C1-INH, ITIH4, AT and alpha-1-antitrypsin." (PMID 34458849, 2021). "Plasma proteins including AAT, ABO, APP, FGA, HPX, ITIH4, PON and others showed similar or higher observation frequency in NHP compared to COVID-19." (PMID 37031181, 2023). "Indeed, it has been suggested that, with other proteins such as Azurocidin 1, ITIH4 could help in avoiding the SARS-CoV-2 complete elimination, in the bodies of long-term persistent COVID-19 patients." (PMID 39594201, 2024). "Consistently, proteomic and metabolomics data from CMs revealed several genes (KNG1, TXNIP, ITIH4, TIMP1, SERPING1/2/3, ITGA1, ADAR, and CLIC5 etc.)and molecules (adenosine and inosine) were related with platelet activation, thus, adding antiplatelet might be a possible therapeutic for COVID-19." (PMID 35903092, 2022).
breast carcinoma (9 papers, 2011 to 2024). "Three peptide biomarkers were identified, including ITIH4, and the authors concluded that this protein has diagnostic and prognostic potential for breast cancer." (PMID 39061201, 2024). "With 2D-nanoLC-MS/MS, afamin, apolipoprotein E and isoform 1 of inter-alpha trypsin inhibitor heavy chain H4 (ITIH4) were found to be higher in pre-diagnostic breast cancer (p < 0.05), while alpha-2-macroglobulin and ceruloplasmin were lower (p < 0.05)." (PMID 21871081, 2011). "Of the proteins detected with 2D-nanoLC-MS/MS, afamin, apolipoprotein E and an isoform of ITIH4 were slightly, but significantly higher and alpha-2-macroglobulin and ceruloplasmin slightly, but significantly lower in pre-diagnostic breast cancer samples compared to control samples." (PMID 21871081, 2011). "Common plasma proteins including APOE, ITIH4 and C3 showed significantly different intensity between breast cancer versus ovarian cancer and normal plasma." (PMID 31889940, 2019). "ITIH4 acts as an acute-phase protein, and has been identified in proteomic studies as a serum biomarker that distinguishes women with breast cancer from healthy controls." (PMID 28526811, 2017). "In these studies levels of a 4.3 kDa ITIH4 fragment were found either to be significantly higher, or significantly lower in breast cancer." (PMID 21871081, 2011). "For some of the proteins this may have been a chance finding, but C3adesArg and ITIH4 have previously also been found in relation with symptomatic breast cancer." (PMID 21871081, 2011). "Others, such as COL18A1, TGFBI, FGB, ITIH2, ITIH4, and TNC among others, were overrepresented in 3 of 4 signatures and also expressed in mammary carcinoma xenografts." (PMID 37098922, 2023). "However, the role of Itih4 in breast cancer remains unknown." (PMID 35578660, 2022).
lung carcinoma (9 papers, 2008 to 2025). "FERMT2 together with FKBP3, SMAD9, GATA2, and ITIH4 was constructed as a prognostic signature of lung cancer based on the differential expression of immune genes." (PMID 36253873, 2022). "Downregulation of ITIH4 in cancer tissue was detectable in tumors of the kidney (95%), stomach (63%) and ovary (57%) as well as in colon cancer (54%), lung cancer (52%), rectum cancer (50%), and prostate cancer (75%)." (PMID 18226209, 2008). "Indeed, inter alpha-trypsin inhibitor heavy-chain 4 in combination with CA125 improved upon the sensitivity of CA125 alone for the detection of lung cancer at the early stage." (PMID 36552994, 2022). "Based on these results, seven proteins, CD5L, CLEC3B, SERFINF1, ITIH4, SAA4, SERFINC1, and C20ORF3 (AMAP) were confirmed as being upregulated in EVs and were therefore considered as potential lung cancer biomarkers." (PMID 33808296, 2021). "Meanwhile, there is plenty of evidence that SMAD9, ITIH4 and GATA2 have close connection with the initiation, progression and prognosis of various malignancies including lung cancer." (PMID 33648465, 2021). "In addition, CLEC3B, ITIH4, SERFINF1, SAA4, SERFINC1, and C20ORF3, whose expression was significantly increased in EVs derived from lung cancer patients, can be included as potential biomarkers." (PMID 33808296, 2021).
Obesity (8 papers, 2015 to 2025). Accumulation of substantial excess body fat. "ITIH4 and TIMP2 have been characterized as obesity-associated genes in human." (PMID 31235755, 2019). "Furthermore, interactions between TNNI3K variants and other genetic loci, such as ITIH4, have been linked to childhood obesity risk, suggesting that TNNI3K may influence obesity through complex genetic networks." (PMID 41082226, 2025). "Higher expression of ITIH4 may be led by HCC development via persistent systemic inflammation due to obesity or metabolic syndrome, but not via complete cirrhosis caused by hepatitis virus infection." (PMID 31238892, 2019). "In summary, in our sample of Chinese children, we replicated eight adult East Asian obesity-related loci (in/near FTO, MC4R, GNPDA2, PCSK1, SEC16B, MAP2K5, ITIH4 and BDNF) in the same direction of effect as previous reports in adults." (PMID 29212175, 2017). "The obesity SNP rs2710323, together with two diabetes SNPs, rs2590838 (r2, 0.78) and rs1108842 (r2, 0.8), are located in loci that regulate genes (TMEM110, MUSTN1, ITIH4, NEK4, GNL3, PBRM1, and NT5DC2) within a 300 kb genomic region on chromosome 3." (PMID 29081791, 2017).
liver fibrosis (7 papers, 2012 to 2025). "ITIH4 is a protease inhibitor involved in inflammation and was found as a biomarker for liver fibrosis." (PMID 38032942, 2023). "A recent study, using proteomic analysis of serum from adult patients with chronic HCV infection, revealed that inter-alpha-trypsin heavy chain 4 (ITIH4) was a candidate to predict liver fibrosis." (PMID 25295185, 2014). "We aimed to investigate serum level of inter-alpha-trypsin inhibitor heavy chain 4 (ITIH4) and its relation to liver fibrosis and viremia in children with chronic HCV." (PMID 25295185, 2014).
gastric cancer (6 papers, 2009 to 2025). A primary or metastatic malignant neoplasm involving the stomach. "Notably, ITIH4 maybe as a promising potential diagnostic biomarker in the serum of patients with early gastric cancer." (PMID 40708696, 2025). "We have used LC-MS/MS to identify three of the peaks that are substantially elevated in gastric cancer patients as fragments of inter-alpha-trypsin inhibitor heavy chain 4 (ITIH4)." (PMID 19550422, 2009). "Exosome analysis validated the expression of ITIH4 in the sera of gastric cancer patients, whereas it was absent in the sera of healthy individuals." (PMID 40708696, 2025).
mastitis (6 papers, 2014 to 2023). Inflammation of breast tissue during lactation or postpartum due to an obstructed duct or infection. "The differentially expressed proteins we discovered in this study, such as COL1A1 and ITIH4, may serve as potential genes for the susceptibility to mastitis in dairy cows." (PMID 25273983, 2014). "And as a newly established acute phase protein, the serum concentration of ITIH4 protein positively correlated with the disease severity of mastitis and its increased concentration was also confirmed in bovine with bovine respiratory syncytial virus infection." (PMID 37941815, 2023). "Recently, studies have focused on identifying new acute-phase protein inter-α-trypsin inhibitor heavy chain 4 (ITIH4) in the milk and whey of cow milk during mastitis." (PMID 37210363, 2023). "Proteins that stand out as logical candidates for further analyses include various APPs and vascular-derived proteins such as C3, C4, TF, ALB, TTR, FGA, and ITIH4 in mastitis whey of E. coli infected cows by 2-DE and label-free methods, respectively." (PMID 36335251, 2022). "In summary, TMT analyses elucidated the role of A2M, Itgb2, Thbs1, Fn1, ITIH4 and other proteins in the host innate response to S. aureus-induced mastitis." (PMID 32365127, 2020). "Of 10 proteins, the expression of ITIH4 protein was increased by 4.55-fold in the mastitis group when compared with the control group." (PMID 25273983, 2014). "Firstly, the relative expressions of COL1A1 (~50 kDa) and ITIH4 (~100 kDa) in the healthy and mastitis-infected cows’ mammary gland tissues were investigated by the Western blotting." (PMID 25273983, 2014). "The result of western blotting implies that 100 kDa fragment of bovine ITIH4 plays an important role in the defense and immune responses to infection of mastitis." (PMID 25273983, 2014).
ovarian carcinoma (6 papers, 2010 to 2022). A malignant neoplasm originating from the surface ovarian epithelium. "While the present study demonstrated the reduced levels of the 39 kDa ITIH4 fragment in the urine of patients with ovarian carcinoma, our previous data showed the up-regulated levels of a 35 kDa ITIH4 fragment in the serum samples of the patients." (PMID 21083881, 2010). "KNG1 and ITIH4 were reported to be significantly downregulated in ovarian cancer." (PMID 35109816, 2022). "In the present proteomic profiling study, the significant reduced excretion of CD59, kininogen-1 and a 39 kDa fragment of ITIH4, and the enhanced levels of a 19 kDa fragment of albumin were detected in the urine samples of patients with ovarian carcinoma relative to those of the control subjects." (PMID 21083881, 2010). "Significant reduced levels of CD59, kininogen-1 and a 39 kDa fragment of inter-alpha-trypsin inhibitor heavy chain H4 (ITIH4), and enhanced excretion of a 19 kDa fragment of albumin, were detected in the urine of patients with ovarian carcinoma compared to the control subjects." (PMID 21083881, 2010). "In case of the 19 kDa albumin fragment, interaction appeared to be detected only in the pooled urine of patients with ovarian carcinoma compared to that of the controls, while the inverse was observed for CD59, kininogen-1 and the 39 kDa fragment of ITIH4." (PMID 21083881, 2010).
cognitive decline (5 papers, 2019 to 2025). "In another study, low levels of SERPINA1, PLG, KLKB1, ITIH4, and APOL1 in serum of patients with lacunar stroke were associated with poor prognosis and increased risk of recurrent stroke or myocardial infarction and cognitive decline." (PMID 31242583, 2019).
coronary heart disease (5 papers, 2015 to 2024). "Modulating tier 1 protein of ITIH4 was suggestively associated with an increased risk of coronary heart disease (p‐value of Wald ratio method = 0.039)." (PMID 38898596, 2024). "Furthermore, our more detailed analysis of Itih4 showed its link to coronary artery disease through the colocalization of genome-wide association studies, splice quantitative trait loci (QTL), and protein QTL signals." (PMID 38289873, 2024). "Significantly upregulated were gene regulators of VSMC differentiation, triggers of cell apoptosis, inflammation and coronary heart disease markers (Itih4, Tppp3, Slc25a39, CD44) in parallel to atheroprotective genes such as Morf4l2." (PMID 35163719, 2022).